CIP2A (cellular inhibitor of PP2A)
Diseases named in the same sentence as CIP2A in open-access papers (continued):
Sharing a sentence is not in itself a finding about the gene and the disease.
cancer (continued). "Next, we set to study the other clinical variables that might be linked to cancers that are positive for both Oct4 and CIP2A, and assessed the differentiation status of the tumors, as low differentiation grade is known to be associated with existence of more stem-like cells." (PMID 25474139, 2015). "To assess whether the overlapping pathway regulation by CIP2A and RAS is biologically meaningful, we analyzed The Cancer Genome Atlas (TCGA) pan-cancer data for potential interactions between CIP2A expression and RAS isoform expression/mutations on patient survival analysis." (PMID 26278961, 2015). "Together, our findings identify CIP2A as a regulator of mitotic processing of under-replicated DNA and provide a framework for understanding context-dependent vulnerabilities in cancer cells." (PMID 42192029, 2026). "CIP2A regulation of EMT is linked to mesenchymal traits that enhance the invasiveness, migration, and metastatic potential in cancer cells and fibrotic and inflammation-associated responses in non-cancerous cells." (PMID 41155727, 2025). "In several previous studies, CIP2A function as a oncogene through upregulation or activation of PP2A target proteins by suppressing PP2A activity in various cancer types." (PMID 41362702, 2025). "Cancerous inhibitor of PP2A (CIP2A) is an oncoprotein that is well documented as being a major player in cancer, primarily by inhibiting the activity of the serine/threonine phosphatase protein phosphatase 2A (PP2A)." (PMID 41155727, 2025). "CIP2A overexpression is ubiquitous in different lines of cancer cells, with overexpression being present in 39–90% of tissue samples in various gastric, bladder, ovarian, tongue, hepatocellular, colon, NSCLC, and chronic myelogenous leukemia cells." (PMID 41155727, 2025). "CIP2A expression was confirmed to be higher in 84% of cancer tissues than in surrounding normal tissues among 69 paired patient tissues." (PMID 41362702, 2025). "Interactions between ELK1 and CIP2A have been reported elsewhere as well, thus accrediting this mechanism with a pan-cancer significance." (PMID 40862737, 2025). "Cancerous inhibitor of protein phosphatase 2A (CIP2A) is an oncoprotein that promotes cancer cell proliferation, invasion, and drug resistance." (PMID 41362702, 2025). "Targeting ELK1-mediated transcription of CIP2A seems to have a pan-cancer significance, since it has been documented in several cancer types." (PMID 40862737, 2025). "CIP2A prevents this complex protein formation, creating an anti-apoptotic environment for cancer cells to proliferate." (PMID 41155727, 2025). "This is of interest, as reactive oxygen species (ROS) (e.g., hydrogen peroxide) can suppress CIP2A expression in cancer conditions." (PMID 41155727, 2025). "CIP2A promotes tumorigenesis by modulating key regulators of cancer cell proliferation and survival, including PP2A, c-Myc, and E2F1." (PMID 41155583, 2025). "For cancer staging, all patients with high CIP2A expression were in early stages (I or II), compared to 77.1% in the low expression group, with the remaining 22.9% distributed across stages III and IV (p = 0.485)." (PMID 40943297, 2025). "CIP2A is an endogenous protein in human cancer cells that directly interacts to c-Myc and hinders the function of PP2A toward c-Myc S62 induction." (PMID 41154660, 2025). "Since then, studies have shown that CIP2A plays a role in the development and progression of various cancer types, including breast, lung, gastric, colorectal, pancreatic, and hepatocellular carcinomas." (PMID 41362702, 2025). "Given the limited understanding of mitotic DSB repair mechanisms and the ongoing clinical trials targeting Polθ, defining the precise role of the CIP2A-TOPBP1 axis in DNA repair is critical for improving the treatment of cancers." (PMID 41309571, 2025). "Specifically, CIP2A promotes cancer cell proliferation, survival, and migration by inhibiting PP2A-mediated dephosphorylation of key substrates, such as c-Myc." (PMID 41155583, 2025).
cancer (continued). "CIP2A is overexpressed in more than 70% of tumors, which correlates with proliferation, migration, invasion, and treatment resistance in cancer." (PMID 39399646, 2024). "CIP2A modulates cell cycle progression, promotes malignant transformation, and renders cancer cell drug resistance." (PMID 38321019, 2024). "EmCIP2Ah encodes a protein with no discernible functional domains, but which is distantly related to human cellular inhibitor of PP2A (CIP2A), an inhibitor of tumour suppressor activities of protein phosphatase 2A in human cancer, e." (PMID 38333034, 2024). "Inhibition of PP2A by CIP2A prevents dephosphorylation of oncoproteins involved in proliferation of cancer cells and tumor growth." (PMID 38999976, 2024). "Aside from CIP2A, PP2A methylesterase 1 (PME-1) has also been considered an endogenous PP2A inhibitor associated with various human cancers." (PMID 38542160, 2024). "Protein phosphatase 2A (PP2A) inhibitors, known as cancer inhibitors of protein phosphatase 2A (CIP2A), play a crucial role in developing various cancers." (PMID 39247603, 2024). "On the other hand, several studies have indicated that the silencing of CIP2A/p90 by small interfering RNAs (siRNA) inhibited the growth of xenografted tumors of various kinds of cancer cells." (PMID 36911405, 2023). "Thereby, beyond their general relevance to understanding phosphoregulation, the results can guide the development of therapies targeting CIP2A-B56α interaction in cancer, and other CIP2A-related diseases." (PMID 36854761, 2023). "Relevant to oncogenic activity of CIP2A across human cancers, the N-terminal head domain-mediated interaction with B56α stabilizes CIP2A protein." (PMID 36854761, 2023). "The binding complex of SET and CIP2A with PP2A remains to be further investigated in cancer research." (PMID 37097392, 2023). "Although interaction of green tea catechin with SET or CIP2A remains to be investigated, numerous scientists reported that human cancer stem cells are a target for cancer prevention using EGCG." (PMID 37097392, 2023). "Further, the results unfold a structural determinant for the oncogenic activity of CIP2A, potentially facilitating therapeutic modulation of CIP2A in cancer and other diseases." (PMID 36854761, 2023). "Of these, CIP2A is widely over-expressed in different human cancer types and drives tumour growth both in xenograft and transgenic mouse models." (PMID 36854761, 2023). "Third, combination of two types of proteomics analysis with bioinformatics analysis confirmed that CIP2A inhibits B56α binding to LxxIxE motif substrates in cancer cells." (PMID 36854761, 2023). "The results also provide clear cues for the development of novel targeted cancer therapeutics by revealing structural determinants behind oncogenicity of CIP2A." (PMID 36854761, 2023). "This suggests that overexpression of SET and CIP2A induces strong inhibition of PP2A activity in human cancer cells, as okadaic acid does." (PMID 37097392, 2023). "Ets1, as the transcription factor, can mediate high CIP2A/p90 expression in human cancers through increased activity of the EGFR-MEK1/2-ERK pathway." (PMID 36911405, 2023). "CIP2A has been shown to activate Akt signaling via inhibition of Akt dephosphorylation in different types of cancer, including lung cancer." (PMID 37097392, 2023). "Many previous studies have also demonstrated that CIP2A/p90 can be used as a potential therapeutic cancer target." (PMID 36911405, 2023). "To test the cancer relevance of the N-terminal head domain of CIP2A, we created MDA-MB-231 single cell clones carrying K21A mutation by CRISPR/Cas9." (PMID 36854761, 2023). "Collectively, these data demonstrate that the N-terminal head domain of CIP2A mediating interaction with B56α is a critical determinant of full-length CIP2A protein expression in cancer cells." (PMID 36854761, 2023).
cancer (continued). "CIP2A silencing enhanced the sensitivity of cancer cells to DCT by strengthening drug-induced cell growth inhibition and apoptosis." (PMID 37065867, 2023). "First, single point mutants of CIP2A head domain amino acids mediating B56α binding dramatically impacted CIP2A protein expression in cancer cells." (PMID 36854761, 2023). "CIP2A also broadly regulates cancer cell therapy responses, and its over-expression clinically correlates with relapse from kinase inhibitor therapies." (PMID 36854761, 2023). "Okadaic acid class of tumor promoters are transformed into endogenous protein inhibitors of PP2A, SET, and CIP2A in human cancers." (PMID 37097392, 2023). "The inhibition of autophagy by mTORC1 in cancer cells is activated by the cancerous inhibitor of PP2A (CIP2A), which is overexpressed in EC." (PMID 35052471, 2022). "Previous studies have demonstrated that CIP2A is overexpressed in various human malignancies, promotes the initiation and proliferation of cancer cells as well as acting as a prognostic marker in multiple cancers." (PMID 34984583, 2022). "Recent studies have shown that silencing of CIP2A by small interfering RNAs (siRNA) inhibits the growth of xenografted tumors of various types of cancer cells." (PMID 36555359, 2022). "The cancerous inhibitorof protein phosphatase 2A (CIP2A)is anoncoprotein found overexpressed in many types of cancer." (PMID 36255265, 2022). "Consistent with our previous results from cancer cells, the Chk1 phosphorylation on serine 345 was highly correlated with levels of DNA damage and CIP2A expression." (PMID 35286657, 2022). "CIP2A is able to promote the growth of cancer cells through the inhibition of dephosphorylation of PP2A substrates involved in cancer development." (PMID 36555359, 2022). "There are three major endogenous cellular inhibitors that regulate PP2A activity: Inhibitor 2 of PP2A (I2PP2A or SET), CIP2A and PME1, all of which have been heavily implicated in tumor promotion and are overexpressed in many cancer types." (PMID 35118387, 2022). "In this study, we also investigated the influence of autophagy on cancer progression through the CIP2A/mTORC pathway." (PMID 35052471, 2022). "The oncoprotein CIP2A is overexpressed in several types of tumors and promotes the proliferation and transformation of cancer cells." (PMID 36555359, 2022). "Recent studies demonstrated an overexpression of CIP2A in several cancer cells, such as tumors of the stomach, esophagus, colon and pancreas, renal cell cancer and ovarian and cervical cancer." (PMID 36555359, 2022). "Analyses of large-scale cancer genomics datasets showed significantly higher expression of SET and CIP2A in various cancers than in their corresponding normal tissues." (PMID 36463234, 2022). "There are also reports showing that CIP2A regulates cancer cell behavior through inhibiting PP2A activity." (PMID 33948919, 2021). "CIP2A, the more heavily studied of the two, is overexpressed in ~40% to 90% of patients across different cancer types." (PMID 34129940, 2021). "High level of the oncogene CIP2A occurs frequently in many cancer types and correlates with malignant growth and clinical aggressiveness." (PMID 33948919, 2021). "Cancerous inhibitor of protein phosphatase 2A (CIP2A) plays a critical role in the pathogenesis of various types of cancer." (PMID 33948919, 2021). "Overexpression of cancerous inhibitor of protein phosphatase 2A (PP2A) (CIP2A) protein is an adverse prognostic indicator in many cancers." (PMID 33947031, 2021). "Increasing evidence has revealed a close correlation between cancerous inhibitor of protein phosphatase 2A (CIP2A) and cancer progression." (PMID 32321509, 2020). "Cellular inhibitor of protein phosphatase 2A (CIP2A) is a human oncoprotein that can promote cancer cell growth and apoptosis resistance." (PMID 32810922, 2020).
cancer (continued). "Protein phosphatase 2A (CIP2A) is another oncogene factor participating in the malignancy of cancer cells and enhancing their growth and proliferation." (PMID 32784981, 2020). "PP2A is often lost or inactivated in cancer through the induction of expression of endogenous inhibitors of PP2A such as CIP2A." (PMID 32512786, 2020). "The uncovered mutual regulation between Cip2a and miR-301a points toward new prognostic and therapeutic options by using components of the Cip2a/E2F1/miR-301a/ERK loop as potential key targets to restrict cancer progression of TNBC." (PMID 31762806, 2019). "CIP2A directly associates with and blocks the B56 regulatory subunits of PP2A complex, and importantly, high expression of CIP2A is correlated with overexpression of EGFR in the certain cancer systems." (PMID 30791455, 2019). "Comparing with paracancer tissues, the IRSs indicated that CIP2A was highly expressed in EGJA cancer cells." (PMID 31534561, 2019). "In EGJA tissues, CIP2A was extensively expressed in cancer cells while in paracancers CIP2A was restricted to the fundic glands." (PMID 31534561, 2019). "Since CIP2A is commonly overexpressed in several cancers, it has become an interesting therapeutic target in order to re-activate PP2A." (PMID 31214504, 2019). "In summary, the okadaic acid class of tumor promoters are transformed into SET and CIP2A, which induce tumor promotion, progression and inflammation in various human cancer cells, which are the results of some life-style related diseases." (PMID 30341686, 2018). "We showed a mechanistic link between miR-548b-3p and CIP2A, which has been reported as an important oncogene in various human cancers." (PMID 30671469, 2018). "The results showed that elevated CIP2A expression was significantly associated with poor OS and DFS in these performed types of cancer." (PMID 30044786, 2018). "This will help us to understand the molecular mechanism of SET and CIP2A overexpression in cancer cells." (PMID 30341686, 2018). "Clinical relevance of CIP2A high-expression would be further considered as a prognostic marker in cancer patients." (PMID 30044786, 2018). "Literature shown that CIP2A inhibited the tumor suppressor protein PP2A which downregulated phophorylation of AKT, a hallmark of cancers and stabilized the proto-oncogene, MYC in tumor cells." (PMID 30044786, 2018). "Recent studies showed that CIP2A regulates cell proliferation and migration in many types of cancer." (PMID 30063110, 2018). "CIP2A was first found as a 90 kDa protein (p90) in human hepatocellular carcinoma, and the expression of endogenous p90 was also observed in cancer cell lines such as HeLa and normal keratinocytes; human p90 gene is localized in chromosome region 3q13.13." (PMID 30341686, 2018). "The biological effects of CIP2A are largely dependent on its stabilization of c-Myc oncoprotein, which drives cancer cell proliferation by upregulating cyclins and downregulating p21." (PMID 30671469, 2018). "Endogenous protein inhibitors of PP2A, SET and CIP2A have led to a new strategy for treatment of cancer, based on evidence that SET and CIP2A knockdowns with siRNA or RNAi and SET antagonists, such as OP449 and FTY720, significantly reduced tumor growth." (PMID 30341686, 2018). "CIP2A was previously shown to block PP2A activity leading to enhanced cancer cell signaling such as those mediated by Akt, MYC and E2F1." (PMID 28884018, 2017). "The relatively low binding affinity between CIP2A peptide and the B′ subunits is consistent with the fact that its cancer-promoting activity requires the presence of an increased level of CIP2A to outcompete interactions with substrates." (PMID 28884018, 2017). "This is consistent with a report showing that celastrol, a natural compound with anti-cancer properties, significantly inhibits pAkt and targets CIP2A protein binding to the E3 ligase CHIP, which results in proteasomal degradation." (PMID 28938602, 2017).
cancer (continued). "Cancerous inhibitor of protein phosphatase 2A (CIP2A), a human oncoprotein dysregulated in several cancer types, is supported to have prominent effects on cancer cell proliferation." (PMID 28521777, 2017). "Inhibiting CIP2A decreases cancer cell viability and anchorage-independent growth and induces apoptosis." (PMID 27144172, 2016). "Cancerous inhibitor of PP2A (CIP2A) is a human oncoprotein that regulates cancer cell viability and anchorage-independent growth and induces apoptosis." (PMID 27144172, 2016). "The oncoprotein Cancerous Inhibitor of Protein Phosphatase 2A (CIP2A) is overexpressed in most malignancies and is an obvious candidate target protein for future cancer therapies." (PMID 27100879, 2016). "Based on the experimental evidence that CIP2A has clinical relevance in the progression of the disease it has been regarded that CIP2A inhibitors have potential for use in the treatment in cancers." (PMID 27144172, 2016). "CIP2A is also an oncoprotein overexpressed in several cancers including CRCs where it inhibits the activity of oncosuppressor PP2A that controls cell cycle and apoptosis." (PMID 27029072, 2016). "Xenograft tumors from lapatinib treatment group showed reduced expressions of CIP2A, p-Akt, and ki-67 in the cancer cells population, defined by HE stain." (PMID 26824320, 2016). "To date, numerous studies have demonstrated that CIP2A is a critical inhibitor of PP2A tumor suppressor activity in various human cancer types." (PMID 27100879, 2016). "Since its original characterization in 2007 as an oncogenic PP2A inhibitor protein, CIP2A has been documented to be a clinically relevant oncoprotein in the vast majority of solid and hematological human cancers tested." (PMID 27100879, 2016). "Clinically, high CIP2A expression correlates with worsened patient survival in more than dozen different cancer types." (PMID 25474139, 2015). "CIP2A promotes cancer cell proliferation and renders cancer cells resistant to therapy-induced apoptosis or senescence." (PMID 25650660, 2015). "Although many studies have demonstrated the overexpression of CIP2A in cancer cell lines, few studies had examined the expression in immortalized cell line." (PMID 26560124, 2015). "Cancerous inhibitor of protein phosphatase 2A (CIP2A) is an important oncogene contributing to cancer progression partially by regulating cMYC and AKT." (PMID 25663244, 2015). "High expression of CIP2A, NRAS, and to lesser extent KRAS was associated with poor prognosis in TCGA pan-cancer data set." (PMID 26278961, 2015). "In this study using patient-derived prostate epithelial cultures (PPECs) and over three hundred clinical samples, we identify CIP2A to be a common denominator for AR and cancer SC-signaling functionality." (PMID 25965834, 2015). "Although, overexpression and a functional significance of CIP2A in androgen-independent cancer SCs implied AR-independent effects of CIP2A, we also have strong evidence for AR-mediated CIP2A regulation in AR-responsive cells." (PMID 25965834, 2015). "Cancerous inhibitor of PP2A (CIP2A) is a recently characterized oncoprotein, which promotes cancer cell proliferation." (PMID 26560124, 2015). "The expression of CIP2A in the cancer stem-like cell (SC) population, was increased by about three-fold in HN-PC-SCs and by about thirty-fold in CRPC-SCs compared to BPH-SCs." (PMID 25965834, 2015). "Together we demonstrate that CIP2A is a novel Oct4 target gene in stem cells and in human cancer cell lines." (PMID 25474139, 2015). "Our study of CIP2A-mediated cell proliferation partially through priming JNK signaling for cell proliferation rather than cell apoptosis expanded the understanding of oncogenic function of CIP2A in cancer progression." (PMID 26560124, 2015). "The latest finding of CIP2A in controlling cell-cycle progression dramatically advanced our understanding of CIP2A in cancer progression." (PMID 26560124, 2015).